EGF (epidermal growth factor)
Diseases named in the same sentence as EGF in open-access papers (continued):
Sharing a sentence is not in itself a finding about the gene and the disease.
lung carcinoma (continued). "Recent studies have shown that cannabis derivatives suppress epidermal growth factor (EGF) and its downstream pathways in human lung cancer cells that cause blockage of tumor cell proliferation and migration." (PMID 33446187, 2021). "Suppressing FUT1 expression in gastric, breast and lung cancer cells reduced the expression of ErbB2, inhibited ErbB2 phosphorylation and EGF-induced ERK1/2 activation." (PMID 34069424, 2021). "It has been confirmed that PTS inhibits the proliferation of lung cancer cells in mice by inhibiting epidermal growth factor signaling, which reduces downstream Akt phosphorylation." (PMID 33623100, 2021). "Particularly in lung cancer, it would be interesting to see if EGF levels vary between non-small cell lung cancer versus small cell lung cancer." (PMID 34115785, 2021). "CD90 and CD133 have been demonstrated to possess the traits of CSCs in lung cancer cells, including clonosphere growth in serum-free medium containing EGF, rapid in vivo tumorigenicity, and resistance to chemoradiotherapy." (PMID 34900727, 2021). "Patients with an epidermal growth factor mutation (EGFR), a subgroup of the patients with lung cancer, seem to develop more bone metastases than other patients with lung cancer." (PMID 34201833, 2021). "Our studies showed that BASP1 knockdown decreased calcium influx in lung cancer cells treated with EGF, suggesting that BASP1 enhanced EGFR signaling and calcium influx to increase cell migration." (PMID 33042262, 2020). "Taken together, this study clearly demonstrates that the IRBIT protein, which binds to NBCn1, plays a positive role in the migration of lung cancer cells by maintaining stable NBCn1 expression in the plasma membrane by mimicking the stimulatory effect of EGF." (PMID 32867284, 2020). "Reportedly, in lung cancer cells, arsenic exposure upregulates the levels of heparin binding-EGF (an EGFR ligand) and stimulates an activating phosphorylation of EGFR (p-EGFR at Tyr 1173)." (PMID 32695675, 2020). "MTT proliferation, colony formation, migration and invasion assays and immunoblotting assay in NCI-H358 and A549 cell lines suggested that OTUD7B enhances EGF-induced Akt signal transduction and promotes lung cancer cell proliferation and migration." (PMID 31572671, 2019). "In contrast to normal epithelial cells, EGF stimulation of lung cancer cell lines that lack DUOX1 promotes EGF-induced EGFR internalization and nuclear localization, associated with induction of EGFR-regulated genes and related tumorigenic outcomes." (PMID 30890751, 2019). "It has recently been shown that SP-D also plays a role in the control of lung cancer progression via epidermal growth factor (EGF) signaling." (PMID 30127783, 2018). "Dysregulation of EGF/EGFR signaling pathway is a well-known critical factor of lung cancer tumorigenesis and for the poor prognosis of this cancer." (PMID 29681982, 2018). "FF interferes with lung cancer cells’ diapedesis through the activation of ROS-dependent signaling that inhibits the Cx43/EGF/ERK1/2-dependent signaling axis." (PMID 30274176, 2018). "In this study, the antimigration and anti-invasion properties of propolin C, a biological active compound of Taiwanese propolis, were examined in EGF/EGFR-regulated EMT in lung cancer." (PMID 29681982, 2018). "In lung cancer cells, Rab35 was found to act as downstream of EGF to promote the formation of RUSC2-GIT2 complex, leading to directed cell migration." (PMID 30524285, 2018). "A549 lung cancer cells were pretreated with serial dosages of propolin C (2.5, 5, 7.5, and 10 μM) for 30 min and then stimulated with 50 ng/mL of EGF for 24 h." (PMID 29681982, 2018). "Consistent with the role of NEDD4, cathepsin B is pivotal for both basal and the EGF-stimulated lung cancer cell migration." (PMID 29455656, 2018). "This piece of data suggests that lysosomal function is required for the EGF-dependent lung cancer A549 cell migration." (PMID 29455656, 2018).
lung carcinoma (continued). "Lu99 cells showed high intrinsic PD-L1 levels and a strong response to EGF among the three lung cancer cell lines studied." (PMID 30126206, 2018). "This is because IFN-γ is the strongest stimulator of PD-L1 expression, and EGF and EGF receptor (EGFR) mutations induce PD-L1 expression with lung cancer progression." (PMID 30126206, 2018). "AQP3 knockdown in skin and lung cancer cell lines reduced EGF-induced H2O2 influx, and attenuated EGF signaling cascades, reducing migration and growth." (PMID 29922644, 2018). "In present studies, the anti-migration and anti-invasion activities of propolin C in EGF/EGFR-mediated EMT in lung cancer cells were examined." (PMID 29681982, 2018). "A549 lung cancer cells were pretreated with serial dosages of propolin C for 30 min and then incubated with EGF for 24 h." (PMID 29681982, 2018). "In this research article, we demonstrated that NEDD4 interacts with EGFR upon EGF stimulation in lung cancer cells." (PMID 29455656, 2018). "Meanwhile, EGF-induced in vitro migration and invasion activities were dose-dependently inhibited in A549 lung cancer cells pretreated with propolin C." (PMID 29681982, 2018). "Our previous studies have demonstrated that EGF can stimulate Rab35 activation in lung cancer and ovarian cancer cells." (PMID 30524285, 2018). "Recently, SP-D has been shown to suppress lung cancer progression via interference with the epidermal growth factor signaling." (PMID 30127783, 2018). "This notion of optimal levels of Ca2+ flux being important was supported by a study in which overexpression of Orai1 in A459 lung cancer cells inhibited EGF-mediated cell proliferation." (PMID 29568366, 2018). "While EGF induced a significant enhancement of migration cell numbers, treatment with chloroquine diminished the EGF-dependent lung cancer cell migration." (PMID 29455656, 2018). "The EGF-induced endocytic degradation of EGFR was examined in a panel of lung cancer cells using immunoblotting." (PMID 29976202, 2018). "So we first tested the effect of the lysosomal inhibitor chloroquine on the EGF-stimulated migration of lung cancer A549 cells using a transwell assay." (PMID 29455656, 2018). "In our hands, FF interfered with the diapedesis of lung cancer cells via the ROS-dependent inhibition of cooperative Cx43/EGF/ERK1/2-dependent signaling between lung cancer and endothelial cells." (PMID 30274176, 2018). "Our study suggests a pathway differs from mTOR cascade in that EGFRhigh lung cancer cells survive Met with sustained phosphorylation of EGFR in response to EGF, and increased sensitivity to Erlo, one of the most wildly used EGFR-TKIs at present in the clinic." (PMID 29312591, 2017). "The performance of this package was tested on microarray data derived from lung cancer cells stimulated with epidermal growth factor (EGF)." (PMID 28088176, 2017). "DDIAS knockdown suppresses lung cancer cell invasion by decreasing β-catenin protein level on EGF exposure." (PMID 27660814, 2016). "The activation of EGFR with the treatment of EGF in lung cancer cells was positively correlated with the phosphorylation of TOPK." (PMID 26745678, 2016). "The protein expression levels of cyclin D1 and Cdc2 were also significantly decreased after TOPK silencing in lung cancer cells exposed to EGF." (PMID 26745678, 2016). "Specifically, EGF pathway over-activation, caused by such as EGFR mutation, has been identified as a prevalent mechanism for the onset and progression of lung cancers." (PMID 26926465, 2016). "While performing this study, another investigation was published showing no impact of URB597 (0.2 μM) and Met-F-AEA (10 μM), a stable AEA analogue, on the invasion of lung cancer cells that was induced by epidermal growth factor." (PMID 26930716, 2016). "In mouse primary lung cells, EGF increased the expression and secretion of IL10, and in the EGF-treated lung cancer cells, IL10 secretion was also increased." (PMID 26956044, 2016).
lung carcinoma (continued). "One important aspect of lung cancer-related mutant EGFR is that the protein undergoes impaired C-cbl mediated degradation stimulated by EGF." (PMID 26646697, 2016). "Consistent with data in HeLa cells, inhibition of ERK5 suppressed DDIAS transcription on EGF exposure in lung cancer cell lines." (PMID 27660814, 2016). "Lung cancer tumorspheres are typically isolated in serum-free media supplemented with external mitogens such as epidermal growth factor (EGF), basic fibroblast growth factor (bFGF), and insulin." (PMID 26880969, 2016). "This suggested that overexpressed wt-EGFR mimicked mutant EGFRs seen in lung cancer patients, which are less responsive to EGF stimulation mediated downregulation." (PMID 26646697, 2016). "YangZheng XiaoJi also exhibited an effect on HGF- and HGF/EGF-induced cellular migration on lung cancer cells and impacted on the phosphorylation of the HGF receptor, cMET." (PMID 26310485, 2015). "Inhibition of the TRPM7 channel resulted in reversal of epidermal growth factor (EGF)-induced migration of a lung cancer cell line and inhibited basal migration of the cells in the absence of EGF." (PMID 25852478, 2015). "To validate our finding that CIP2A regulates JNK phosphorylation in lung cancer cells, we treated the cells with EGF to activate the growth factor-induced JNK activation for 15 mins." (PMID 26560124, 2015). "SNX-2112, a novel small molecule inhibitor of HSP90, reduces EGF cross-talk and activation of the c-Met receptor via c-Met degradation in lung cancer cells." (PMID 25780909, 2015). "In the present study, epidermal growth factor (EGF)-modified gelatin nanoparticles (EGNP) was developed to administer doxorubicin (DOX) to lung cancers." (PMID 25266303, 2014). "We found that EGF was involved in the development of the lung cancer inflammatory microenvironment through the over-production of CXCL8 associated with the activation of EGFR pathway." (PMID 24629040, 2014). "Present study aimed at treating lung cancers by the inhalation of DOX-loaded EGF-conjugated gelatin nanoparticles (EGNP) by nebulizer technique." (PMID 25266303, 2014). "Together, these results indicate that endogenous EGFR can phosphorylate GPRC5A at four identified tyrosine residues (Y317, Y320, Y347 and Y350) in response to EGF stimulation in the lung cancer H1792 cells." (PMID 25311788, 2014). "In summary, we have successfully developed EGF-surface modified gelatin nanoparticles to target EGFR overexpressing lung cancers." (PMID 25266303, 2014). "Recent studies in pancreatic cancer and lung cancer cells that express Vav1 clearly showed that Vav1 functions as a GEF for Rac1 GTPase following EGF stimulation." (PMID 25313137, 2014). "Recent studies in pancreatic cancer and lung cancer cells that express Vav1 showed that Vav1 functions as a GEF for Rac1 GTPase following EGF stimulation and that this activity is critical for its function." (PMID 23342133, 2013). "To address this question, we carried out costimulation experiments with EGF and collagen, using Calu1 lung carcinoma cells and mouse Swiss 3T3 fibroblasts." (PMID 23704935, 2013). "Adequate methods to identify which lung cancer patients are most likely to benefit from the targeted drugs against both epidermal growth factor receptor/epidermal growth factor (EGFR/EGF) are needed." (PMID 26317020, 2013). "Both Calu1 cells of human lung carcinoma origin and Swiss 3T3 cells of mouse fetal fibroblast origin migrated in response to EGF in this assay system." (PMID 23704935, 2013). "Collectively our results suggest the existence of a cooperative effect between EGF pathway activation and TWIST1 reactivation in promoting EMT in EGFR mutated lung cancer." (PMID 22272264, 2012). "Taken together, our results demonstrate that CARMA3, via IκB phosphorylation, mediates EGF-induced NF-κB activation in lung cancer cells." (PMID 22615840, 2012).
lung carcinoma (continued). "Our study results clearly demonstrate the essential role of the CARMA3-Bcl10-MALT1 signaling complex in EGF-induced NF-κB activation in lung cancer cells." (PMID 22615840, 2012). "Induction of HAS3 expression by EGF and ErbB2 receptors has also been shown for keratinocytes, prostate and lung carcinoma cells." (PMID 21429221, 2011). "In particular, discoidin is involved in cell survival and migration, is overexpressed in highly-metastatic lung cancer cells, and was shown to be a novel tyrosine phosphorylation substrate of EGF signaling." (PMID 20955590, 2010). "MicroRNA array analysis showed 39 miRNAs were in response to EGF stimulation in lung cancer cells (P < 0.01)." (PMID 19702827, 2009). "Our data are strongly in agreement with previous indication that GAPDH is regulated in response to various stimuli (i.e hypoxia, insulin, mitogen, EGF) and that its transcript is elevated in various cancer tissues, including lung cancer." (PMID 16872493, 2006). "Finally, we show that these SASP factors are likely to functional in vivo, as targeting factors like TGF-β and EGF in lung cancers containing senescent cells appears to inhibit tumour cell growth." (PMID 41497628, 2025). "Given the established role of PYCR1 in regulating EGFR- and TLR-mediated signaling, we investigated whether PYCR1 influences lung cancer progression in response to EGF and TLR agonists." (PMID 41254241, 2025). "However, there is a meta‐analysis study on the EGF gene and lung cancer that included six previous research results, although the loci studied differ from those in this study." (PMID 40696566, 2025). "Distribution of rs1897990 and rs1524106 in EGF gene with adenocarcinoma of lung cancer." (PMID 40696566, 2025). "However, in both colon and lung cancers, EGF promoters were significantly hypomethylated relative to their respective normal tissues, indicating a possible activation of EGF expression through loss of methylation." (PMID 40692603, 2025). "Epidermal growth factor (EGF) overexpression, EGF receptor (EGFR) overexpression and/or activating mutations of its intracellular kinase domains have been identified as drivers in various cancers, including lung cancer." (PMID 39436906, 2024). "Finally, therapeutic effects targeted to PTK2 in lung cancer in response to EGF and TLR agonists were verified by using its inhibitor (Defactinib)." (PMID 38816856, 2024). "Notably, previous studies have demonstrated that EGF can enhance lung cancer cell migration, thus, we also examined the effect of EGF treatment on the migration ability of Tks4-KO cells." (PMID 38985526, 2024). "Additionally, mPEG-PLGA-PLL nanoparticles successfully deliver epidermal growth factor (EGF) and Bcl-2-siRNA genes to target H1299 lung cancer cells, resulting in inhibited tumor growth by reducing Bcl-2 expression in tumor tissues." (PMID 38361919, 2024). "We also innovatively proposed that LAD1 may assign a “K-Ras addiction” phenotype to LUAD tumor cells, and EGF signal activation closely related to lung cancer may belong to one of the carcinogenic signaling pathways." (PMID 36770773, 2023). "The complex of TF and VIIa, as well as the binding of epidermal growth factor to its receptor in cancer cells present in lung cancer, leads to the activation of the mTOR pathway, and the mTOR pathway leads to an increase in the expression of TF in lung cancer and glioblastoma." (PMID 37280670, 2023). "Next, to explore whether EGFR activation reduced sensitivity to ALKi, ALK‐rearranged lung cancer cells were cotreated with the EGFR ligand EGF and ceritinib." (PMID 36423211, 2023). "On the other hand, circHERC1 overexpressing lung cancer cells lost the reactivity to EGF." (PMID 37932766, 2023). "Notably, among them (IL1-β, IL-3, MCP-1, TNF-α), the EGF, the most acknowledged target for lung cancer therapy, emerges." (PMID 36733673, 2023). "NEDD4 is essential for EGF-induced migration of lung cancer cells." (PMID 36923932, 2023).
lung carcinoma (continued). "Furthermore, researchers reported that KIF22 can influence the biological processes of phosphorylation for epidermal growth factor receptor (EGFR), which can weaken EGFR internalization and promote EGF-dependent lung cancer cell proliferation." (PMID 35578724, 2022). "Also, diminished Vav1′s expression in lung cancer cell lines reduced the expression of the growth factors, TGFα and EGF, and CSF-1, which led to reduced tumorigenicity." (PMID 35326399, 2022). "However, we found enhanced inhibitory performance for MBQ-168 in reducing actin cytoskeletal extensions in response to EGF in lung cancer cells." (PMID 36861094, 2022). "Therefore, EGF signaling has been identified as a desirable targetable pathway to inhibit lung cancer growth." (PMID 35235599, 2022). "Interestingly, there was decreased phosphorylation of FAK and AKT in integrin β1–KO A549 cells prior to treatment with EGF, suggesting that integrin β1 signaling plays a role in the basal activation of these pathways in KRAS-mutated lung cancer cells." (PMID 35763345, 2022). "We therefore tested whether CrT/TICs secrete EGF to activate EGFR signalling in differentiated lung cancer cells." (PMID 36504325, 2022). "Interestingly, when lung cancer cells were treated with EGF, we observed an increased proliferation that was reduced in a dose-dependent manner by both AvnA and AvnC, indicating a possible inhibitory role of Avns in EGF signalling pathway." (PMID 35955669, 2022). "However, its larger impact will depend on the smart insertion of immune EGF deprivation into the complex algorithm of lung cancer management." (PMID 34211836, 2021). "Based on the data from A549 cells, blocking TGFβ signals could be more effective in combating invasion and EMT at least in a subset of lung cancer patients, but would still allow for EGF induced migration." (PMID 33777943, 2021). "The levels of EGF in serum of lung cancer patients ranged from 344 pg/ml to1586 pg/ml, the median concentration was 788 pg/ml, and the average concentration was 923 pg/ml, all of which were significantly higher than that of healthy donors (257 ± 168 pg/ml) (data not published)." (PMID 34804932, 2021). "In addition, it is important to mention that alterations in EGF signalling pathway have been observed in several pathologies being lung cancer a paradoxical example of EGFR targeted therapy." (PMID 34655447, 2021). "The combination of CIMAvax-EGF with ICIs may provide a potential therapeutic option for advanced lung cancer in the future, to ensure better tumor control, in terms of the good safety and immunogenic profile of CIMAvax-EGF." (PMID 34201650, 2021). "It would be interesting if these EGFR ligands such as TGF-alpha, amphiregulin or epiregulin, might serve as biomarker in head and neck or lung cancer patients as we found for EGF." (PMID 34115785, 2021). "Thus, lung cancer cells and cancer cells arising in other organs have a high likelihood of simultaneously receiving both TGFβ and EGF signals in an autocrine and paracrine manner." (PMID 33777943, 2021). "It is important to note, however, that stimulation of human A549 lung cancer cells and primary mouse lung cancer cells with several different growth factors (e.g., EGF; FBS; insulin) increased TBK1 S172 phosphorylation, which required TBKBP1 (TBK1 binding protein 1), a TBK1 adaptor protein." (PMID 34245780, 2021). "In this study, we aimed to investigate 1) serum EGF in oncological patients with a head and neck or lung carcinoma at the time of diagnosis and 2) whether serum EGF could be a potential biomarker for tumour response to chemotherapy and 5-year survival." (PMID 34115785, 2021). "To connect the NEDD4-mediated lung cancer cell migration, including both the EGF and the non-EGF dependent lung cancer cell migration, to lysosomal secretion, we examined the effect of CA-074Me, a specific inhibitor of cathepsin B, on lung cancer A549 cell migration using a wound healing assay." (PMID 29455656, 2018).